ENSG00000286239 (novel protein, WDFY1-AP1S3 readthrough)
Gene: Protein-coding gene on chromosome 2 (223,757,258 to 223,945,299, reverse strand). Ensembl gene ENSG00000286239.
Genetic constraint (gnomAD): Missense variants: 188 observed, 206.7 expected, observed/expected ratio (o/e) 0.91, 90% interval 0.81 to 1.03. Synonymous variants: 83 observed, 77.88 expected, observed/expected ratio (o/e) 1.07, 90% interval 0.89 to 1.28.